TRPM4 (transient receptor potential cation channel subfamily M member 4)
Diseases named in the same sentence as TRPM4 in open-access papers (continued):
Sharing a sentence is not in itself a finding about the gene and the disease.
tumor (continued). "To reveal the intra-tumor heterogeneity of malignant epithelial cells, we categorized the obtained cells into four subtypes: C0 TRPM4+ malignant cells, C1 SLPI+ malignant cells, C2 MIR205HG+ malignant cells, and C3 NEFH+ malignant cells." (PMID 39759507, 2024). "We further evaluated the efforts of TRPM4 on tumor growth of HT29 cells in nude mice in vivo (n=5, respectively)." (PMID 36147460, 2022). "The clinicopathological parameters and the silencing of TRPM4 by promoter methylation in CRC indicates that TRPM4 is probably a tumor suppressor." (PMID 36147460, 2022). "All results above indicated that TRPM4 acts as a tumor suppressor in CRC via impeding cell proliferation as well as metastasis." (PMID 36147460, 2022). "Above results have validated that TRPM4 expression plays an important role in tumor migratory and cytoskeletal regulation as well as Ca2+-calpain activation." (PMID 36147460, 2022). "Since the strong relation between calcium and tumor migration, we studied the effort of TRPM4 expression on cytosolic Ca2+ levels." (PMID 36147460, 2022). "In colorectal cancer (CRC), the overexpression of TRPM4 has been related to characteristic adverse tumor patterns, such as epithelial-mesenchymal transition and hence infiltrative growth." (PMID 36844925, 2022). "The results showed that 14 of 21 pairs (66.7%) demonstrated reduced TRPM4 protein expression in the tumor compared with the adjacent normal tissue." (PMID 36147460, 2022). "In most studies, TRPM4 protein expression levels were reported to be increased in tumor samples compared to healthy tissue." (PMID 33562811, 2021). "The authors provided evidence for decreased expression of TRPM4 in tumors with advanced tumor stage, high grade, myometrial invasion, and lymph node metastases." (PMID 34936030, 2021). "Out of 189 DLBCL cases, 26% exhibited 10–100% TRPM4-positive tumor cells, and the high TRPM4 expression in activated B cell-like DLBCL subtype was associated with a reduced overall and progression-free survival." (PMID 35056097, 2021). "Increased TRPM4 staining intensity in the membrane and cytosol of tumor cells was significantly correlated with a worse patient prognosis." (PMID 34680485, 2021). "Given the fact that TRPM4 is upregulated in tumor buds of CRC, markers of disease progression, this can become interesting for the development of new therapies." (PMID 34771564, 2021). "TRPM4 inhibition revealed potential anti-tumor effects by directly targeting the bCSC subpopulation." (PMID 34680485, 2021). "In another study, a significant increase in TRPM4 mRNA expression in tumor samples compared to the controls and increased TRPM4 levels in the less differentiated and more aggressive tissue samples categorized with a higher Gleason score (>7) were reported." (PMID 33562811, 2021). "Immunohistochemical analysis of tissue microarrays from 379 CRC patients revealed that TRPM4 is highly expressed in tumor buds, which are clusters of up to five cells that detach from the original tumor site." (PMID 34771564, 2021). "Tumor characteristics and clinical parameters were statistically analyzed according to TRPM4 staining intensity." (PMID 31441200, 2019). "Analysis of tumor features from 379 patients revealed that high levels of TRPM4 protein were related to aggressive tumor features, including high numbers of tumor buds—which is a sign of EMT, metastasis, and more aggressive infiltrative growth patterns in CRC." (PMID 31441200, 2019). "Overall, high TRPM4 protein expression levels correlated with a high number of tumor buds, and an infiltrative growth pattern (low percentage of TBC)." (PMID 31441200, 2019). "Furthermore, utilizing algorithms such as CIBERSORT and xCell, we systematically analyzed the relationship between NECSO scores, TRPM4 expression levels, and tumor immune cell infiltration characteristics." (PMID 41584840, 2025).
tumor (continued). "Furthermore, TRPM4 overexpression synergized with the sodium overload inducer Necrocide-1 (NC1) to enhance anti-tumor efficacy." (PMID 41584840, 2025). "Additionally, TRPM4 and SLC9A1 were associated with tumor staging: their levels were upregulated in T3-T4 stage BRCA patients compared to T1-T2 stage patients." (PMID 41235237, 2025). "Moreover, ectopic expression of TRPM4 inhibited tumor growth and metastasis both in vitro and in vivo." (PMID 36147460, 2022). "In a summary, these results suggest TRPM4 may regulate tumor cell migration through cytoskeleton restructure and suppresses CRC carcinogenesis in vivo." (PMID 36147460, 2022). "In order to assess whether overexpression of TRPM4 was instrumental in CRC migration and invasion, wound-healing assays and transwell migration were performed and showed that TRPM4 also possesses inhibitory activity of tumor migration and invasion (p<0.05)." (PMID 36147460, 2022). "We found that TRPM4 was notable downregulated in tumor tissues in these datasets." (PMID 36147460, 2022). "The dual-targeting of TRPM4 in combination with any of its interaction partner proteins or tumor-specific membrane proteins with bispecific-antibodies carrying toxins could diminish the risk of unwanted side effects in other tissues of the body." (PMID 33562811, 2021). "TRPM4 protein was reported to be highly expressed in tumor buds, and high expression of TRPM4 was correlated with a higher number of tumor buds and an increased percentage of the infiltrative tumor border configuration." (PMID 33562811, 2021). "We also found that IFNGR2, IQCE, TRPM4, and SLX4 could be associated with SNU-16 derived tumor growth in female mice by endogenous E2." (PMID 34257587, 2021). "Moreover, high TRPM4 expression was correlated with high numbers of tumor buds, as well as an infiltrative pattern of the tumor border." (PMID 34771564, 2021). "However, a recent study investigating TRPM4 protein expression levels in CRC tissues showed that its high expression correlates with high numbers of tumor buds and an increased percentage of infiltrative tumor border configuration." (PMID 32182937, 2020). "Another candidate for a novel biomarker could be TRPM4, which was shown to be highly expressed in tumor buds in CRC cancer tissues." (PMID 32182937, 2020). "Our present data demonstrated that TRPM4 protein was expressed in CRC tumor tissue." (PMID 31441200, 2019). "Indeed, TRPM4, which we found significantly down-regulated in tumor tissues (fold-change < −1) in the microarray dataset, was also down-regulated with a fold-change of −0.8 in the TCGA dataset." (PMID 31010205, 2019). "Overall, our data highlight a functional role of TRPM4 in tumor cell migration and invasion, which may contribute to tumor budding." (PMID 31441200, 2019). "For these patients, TRPM4 signal intensities were evaluated in areas of tumor, PIN, and BPH." (PMID 26496025, 2015). "Actually, decreased TRPM4 expression is detected in EC tumors with advanced stage, high-grade, lymph node metastasis, and distant metastasis and depletion of TRPM4 in EC cells increases proliferation and metastasis, suggesting that this important CC could be a tumor suppressor." (PMID 37375748, 2023). "hypothesize the involvement of TRPM4 in cell chemoresistance, tumor recurrence, and metastasis." (PMID 36844925, 2022). "First, the functional validation of TRPM6 and TRPM4 was restricted to two CRC cell lines (HCT116 and SW480), and in vivo animal models are needed to confirm their roles in tumor progression." (PMID 41562086, 2025). "Specifically, TRPM1 and TRPM2 were upregulated in tumor tissues, whereas TRPM4, TRPM6, TRPM7, and TRPM8 were downregulated in the tumor group." (PMID 41562086, 2025). "To systematically identify molecules significantly correlated with TRPM4 expression, we calculated the Pearson correlation coefficients (PCCs) between TRPM4 and genome-wide gene expression profiles using transcriptomic data from TCGA-KIRC tumor samples." (PMID 41584840, 2025).
tumor (continued). "For example, the intermodular crosstalk between Light-Yellow genes, TRPM4 and STX18, point to interactions between tumor proliferation and immune responses/vesicular trafficking." (PMID 39596419, 2024). "As described in this review, several miRNA/TRP channel pairs seem to play a key role in tumor biology such as TRPM1, TRPM3, and TRPM4." (PMID 36844925, 2022). "Further analysis of tumor immunologic characteristics and the correlation of ferroptosis with UVM revealed that TRPM4 and TRPV2 are considered as two novel prognostic biomarkers and promising targeted therapy in UVM." (PMID 36081847, 2022). "The TRPM4 gene is highly expressed in CRC tumor buds, contributing to the proliferation and invasion of tumor cells." (PMID 35158942, 2022). "In contrast, increased TRPM4 mRNA expression was observed in EC biopsies with a low EMT status and less aggressive tumor phenotypes." (PMID 34936030, 2021). "Elevated TRPM4 protein expression levels are present in CRC tissues, characterized by high numbers of tumor buds and an increased percentage of infiltrative tumor border configuration." (PMID 34771564, 2021). "High expression of TRPM4 and TRPM7 was detected in primary tumor biopsies, while TRPV4, TRPC4, TRPC6 and especially TRPV6 expression was limited, while the expression of TRPC1 and TRPV2 are moderately expressed." (PMID 34936030, 2021). "Therefore, the expression of TRPM4 could potentially add to the detection of tumor buds." (PMID 32182937, 2020). "In the present study, we analyzed TRPM4 protein expression levels in CRC tissue from 379 patients and examined its correlation with clinical and tumor parameters." (PMID 31441200, 2019). "Here, we investigated tumor tissue microarrays from 379 CRC patients and analyzed TRPM4 protein expression, tumor characteristics, and clinical outcome." (PMID 31441200, 2019). "Finally, this work shows the involvement of TRPM4‐dependent calcium signaling in the regulation of β‐catenin and provides a framework to understand the contribution of a series of ion channels whose expression and/or function is altered in the tumor progression process." (PMID 28614631, 2018). "We find that absence of TRPM4 reduced PCa tumor spheroid size and decreased PCa tumor spheroid outgrowth." (PMID 39821469, 2025). "Prognostic outcomes related to TRPM4 and TRPML2 expression between tissue types, as well as other ion channels, may be further modified by influences from the tumor micro-environment." (PMID 40332161, 2025). "We employed immunohistochemistry to analyze the expression of TRPM4 and SLC9A1 in tumor tissues." (PMID 41235237, 2025). "In our study, TRPM4 was found to be frequently downregulated in CRC cell lines and cases because of CGI methylation in its promoter region and the declined expression significantly related to higher tumor stages." (PMID 36147460, 2022). "The identification of functional TRPM4, TRPV2 expression in UVM may provide new drug targets for the treatment of this aggressive tumor disease." (PMID 36081847, 2022). "Furthermore, either upregulation of miR-150 or knockdown of TRPM4 suppresses proliferation, migration, invasion and EMT in vitro, while in vivo restrains tumor growth and metastasis." (PMID 36844925, 2022). "A study investigating mRNA expression levels of the TRP channels in human CRC tissue versus normal colon mucosa detected an increase in gene expression of TRPM8, TRPV6, and TRPV1 and a lower expression of TRPV4, TRPM4, TRPV3, TRPC6, and TRPV5 in the tumor tissues of CRC compared to normal tissues." (PMID 32182937, 2020). "The imbalance of mRNA versus protein level in Colo205 may also reflect that while TRPM4 mRNA expression in CRC is decreased, we find high TRPM4 protein expression correlated with tumor budding and TBC." (PMID 31441200, 2019).
tumor (continued). "TRPM4, a sodium-permeable channel, likely drives metastasis through calcium signaling dysregulation, while SLC9A1, a sodium-hydrogen exchanger, may acidify the tumor microenvironment to promote therapy resistance." (PMID 41235237, 2025). "(2014) showed that the TRPM4 gene is involved in the progression of the androgen‐independent growth stage, a late step in the progression of this tumor with no satisfactory treatment, indicating that this gene is an important candidate for study as a possible target for therapy in these patients." (PMID 28614631, 2018). "In addition, lack of TRPM4 increased cell death in PCa tumor spheroids." (PMID 39821469, 2025). "In present study, the transient receptor potential melastatin 4 (TRPM4), a calcium-activated nonselective cation channel, is downregulated in CRC as a novel methylated tumor suppressor gene (TSG)." (PMID 36147460, 2022).
cardiac diseases (10 papers, 2017 to 2024). "Nevertheless, the exposure levels reached by compounds in the heart are adequate to warrant testing in models of heart disease at adequate dosing, such as those resulting from TRPM4 gain-of-function mutations." (PMID 39687019, 2024). "Several TRPM4 variants linked to inherited cardiac diseases were shown to cause either gain- or loss-of-function of the channel activity." (PMID 29568272, 2018). "Even if AP parameters are different between mice and human, the model of Trpm4−/− mice might be representative of heart disease related to TRPM4 mutations in human." (PMID 28315637, 2017). "In vitro pharmacological assessments indicate no off-target binding, and the bioavailability in the heart appears sufficient for treatment studies in mouse models of TRPM4-related cardiac diseases." (PMID 39687019, 2024). "Our findings showed that Brg1 modulates TRPM4 channel activity, especially under hypoxic conditions relevant to heart diseases." (PMID 39726787, 2024). "Despite recent findings regarding the functional implications of TRPM4 in cardiac diseases, the molecular and cellular mechanisms leading to altered conduction are poorly understood." (PMID 29568272, 2018). "Additionally, the newly identified Brg1-RUNX1 interaction illustrated the complexity of TRPM4 regulation in cardiac disease." (PMID 39726787, 2024). "Therefore, considering the prevalence of pathologic hypoxia and ischemia in various cardiac diseases, it was crucial to examine the effect of Brg1 on TRPM4 under hypoxic conditions." (PMID 39726787, 2024). "There have been reports indicate that TRPM4 could be modulated by oxidative stress and result in numerous human diseases such as vascular, neurodegenerative or cardiac diseases." (PMID 36147460, 2022). "K914R mutation of TRPM4 is a Ca2+-activated nonselective cation channel linked to human cardiac diseases." (PMID 35813831, 2022). "A potential beneficial effect of inactivating or deleting TRPM4 in other cardiac disease models in the mouse or other species has not been investigated so far." (PMID 33205255, 2020).
cardiovascular diseases (10 papers, 2013 to 2025). "Transient receptor potential (TRP) melastatin 4 (TRPM4) protein is a calcium-activated monovalent cation channel associated with various genetic and cardiovascular disorders." (PMID 39828793, 2025). "This is the first case to closely link TRPM4 mutation to the pathophysiology of human cardiovascular disease." (PMID 29914130, 2018). "Mutation, irregular expression and sustained activation of the Transient Receptor Potential Channel, type Melastatin 4 (TRPM4), have been linked to various cardiovascular diseases." (PMID 26785754, 2016). "TRPM4 is an ion channel associated with various genetic and cardiovascular disorders." (PMID 39828793, 2025). "In addition to the described studies, TRPM4 channels were implicated in other cases of unexpected sudden natural death and cardiovascular disorders." (PMID 33381229, 2020). "On the other hand, TRPM4 expression is upregulated in a variety of cardiovascular diseases, mainly in atrial cardiomyocytes." (PMID 39726787, 2024). "As the research on TRPM4 progresses, more functions will be recognized and intrinsic links between TRPM4 and the development of cardiovascular diseases may be discovered." (PMID 29914130, 2018). "TRPM4 is highly expressed in a number of tissues and organs and involved in complicated physiological and pathological mechanisms, especially in calcium-dependent mechanisms, such as insulin secretion, immune response, respiratory reaction, tumor development, and cardiovascular diseases." (PMID 29914130, 2018). "Notably, inhibition of TRPM4 has shown promise in mitigating arrhythmias induced by hypoxia-reoxygenation in mice and in offering protection against ischemia-reperfusion injury in rat hearts, underscoring its therapeutic potential in cardiovascular disease management." (PMID 39726787, 2024). "Since TRPM4 is a non-selective monovalent cation channel, changes of TRPM4 expression would result in abnormal TRPM4 current in cardiovascular diseases." (PMID 39726787, 2024). "Because transient receptor potential cation channel subfamily M member 4 (TRPM4) is functionally expressed by many cell types in the cardiovascular system and is involved in the pathogenesis of various cardiovascular diseases, we decided to assess its suitability as a target of therapy." (PMID 23936231, 2013).
neurological disorders (7 papers, 2018 to 2025). "In addition, TRPM4 has been linked to several neurological disorders such as experimental autoimmune encephalomyelitis and multiple sclerosis, spinal cord injuries, and traumatic brain injuries." (PMID 29568272, 2018). "The production of monoclonal antibody M4M marks an advancement of our attempt to develop a novel therapy for neurological diseases relating to TRPM4 abnormal functions." (PMID 36380063, 2022). "TRPM4 expression was found upregulated in neurological diseases with hypoxic insult." (PMID 36380063, 2022). "It is possible that these pathological changes result from toxic NMDAR/TRPM4 signaling, as deregulation of glutamate uptake systems, and consequently elevated extracellular glutamate levels that stimulate extrasynaptic NMDARs, is common to many neurological disorders." (PMID 39936986, 2025).
immune diseases (3 papers, 2019 to 2021). "Transient receptor potential melastatin 4 (TRPM4) is widely expressed in various organs and associated with cardiovascular and immune diseases." (PMID 33562811, 2021). "Dysregulations of TRPM4 by either altered expression levels or mutations have been linked to several pathological conditions, including cardiac disorders, immune diseases, and neurological disorders." (PMID 33562811, 2021).
neurodegenerative disease (3 papers, 2020 to 2025). A disorder of the central nervous system characterized by gradual and progressive loss of neural tissue and neurologic function. "This positions them as promising options for treating neurodegenerative diseases and diseases associated with TRPM4 mutations." (PMID 39687019, 2024). "Notably, mitochondrial dysfunction and structural damage—a hallmark of toxic NMDAR/TRPM4 signaling—is common to virtually all neurodegenerative diseases and is believed to be a major promoter of disease progression." (PMID 39936986, 2025). "Recent findings propose compounds that inhibit TRPM4-NMDAR binding as a treatment option for neurodegenerative diseases." (PMID 39687019, 2024). "In summary, while our study provides a solid foundation for the development of TRPM4 antagonists as potential therapeutics for neurodegenerative diseases, addressing these limitations through future research will be critical to realizing their full clinical potential." (PMID 39687019, 2024).
adenocarcinoma (1 paper, 2022). A common cancer characterized by the presence of malignant glandular cells. "It was recently observed on an adenocarcinoma cell line LS174T that knockdown of TRPM4 depresses ROS generation." (PMID 36139640, 2022).
bacterial infection (1 paper, 2021). "The tight control of Ca2+ influx by the TRPM4 channel is critical for response to bacterial infection." (PMID 33809523, 2021).